PTGER1 (prostaglandin E receptor 1)
Description:
Receptor for prostaglandin E2 (PGE2). The activity of this receptor is mediated by G(q) proteins which activate a phosphatidylinositol-calcium second messenger system. May play a role as an important modulator of renal function. Implicated the smooth muscle contractile response to PGE2 in various tissues.
Synonyms: EP1
Tractability: Small molecule: an approved drug acts on it; a high-quality ligand is known; it belongs to a druggable protein family. Antibody: its Gene Ontology location is reachable by antibodies, with high confidence; UniProt places it where antibodies can reach, with medium confidence; UniProt predicts a signal peptide or a membrane-spanning region. PROTAC: a small molecule that binds it is known.
Target class: Lipid-like ligand receptor (family A GPCR); Membrane receptor; Prostanoid receptor; Small molecule receptor (family A GPCR); Family A G protein-coupled receptor
Chemical probes: CHEMBL3127163
Gene: Protein-coding gene on chromosome 19 (14,472,466 to 14,477,272, reverse strand). Ensembl gene ENSG00000160951.
Subcellular location: Cell membrane
Pathways (Reactome):
Signal Transduction: G alpha (q) signalling events; Prostanoid ligand receptors
Gene Ontology:
Molecular function: protein binding; prostaglandin E receptor activity; D1 dopamine receptor binding; G protein-coupled receptor activity; prostaglandin receptor activity
Biological process: response to prostaglandin E; adenylate cyclase-activating G protein-coupled receptor signaling pathway; G protein-coupled receptor signaling pathway; inflammatory response; phospholipase C-activating G protein-coupled receptor signaling pathway; positive regulation of cytosolic calcium ion concentration; adenylate cyclase-activating dopamine receptor signaling pathway; maternal process involved in parturition; micturition; negative regulation of circadian sleep/wake cycle, non-REM sleep; negative regulation of mucus secretion; positive regulation of chondrocyte differentiation; positive regulation of circadian sleep/wake cycle, wakefulness; positive regulation of phospholipase C/protein kinase C signal transduction
Cellular component: plasma membrane; membrane
Genetic constraint (gnomAD): Loss-of-function variants: 15 observed, 10.87 expected, observed/expected ratio (o/e) 1.38, 90% interval 0.91 to 1.89. The synonymous counts are far from expectation, so gnomAD's model fits this gene poorly and the ratio says little. Missense variants: 567 observed, 407.78 expected, observed/expected ratio (o/e) 1.39, 90% interval 1.3 to 1.49. Synonymous variants: 339 observed, 211.87 expected, observed/expected ratio (o/e) 1.6, 90% interval 1.46 to 1.75.
Homologues: Orthologues: chimpanzee PTGER1 (99% identical), macaque PTGER1 (97% identical), pig PTGER1 (89% identical), mouse Ptger1 (85% identical), rat Ptger1 (84% identical), guinea pig PTGER1 (84% identical), tropical clawed frog ptger1 (40% identical), zebrafish ptger1c (39% identical), Drosophila melanogaster CG7497 (21% identical). Paralogues in human: PTGFR (33% identical), TBXA2R (31% identical), PTGER3 (28% identical), PTGER2 (24% identical), PTGER4 (24% identical), PTGIR (23% identical), PTGDR (20% identical).
Diseases named in the same sentence as PTGER1 in open-access papers:
PTGER1 is named in the same sentence as 117 diseases in open-access papers, as found by Europe PMC text mining. Sharing a sentence is not in itself a finding about the gene and the disease. The quoted sentences say what the papers report.
Stroke (7 papers, 2009 to 2024). Sudden impairment of blood flow to a part of the brain due to occlusion or rupture of an artery to the brain. "We previously reported that maternal protein restriction modulates the methylation state of the renal prostaglandin E receptor 1 gene (Ptger1), a key regulator of hypertension, in the stroke-prone spontaneously hypertensive (SHRSP) rat model." (PMID 37125041, 2023).
Hypertension (6 papers, 2015 to 2023). The presence of chronic increased pressure in the systemic arterial system. "Our present study reveals that maternal protein restriction during gestation triggers significant DNA methylation alterations and heightened expression of renal Ptger1, an identified factor associated with hypertension in offspring." (PMID 37764741, 2023). "Overall, we revealed that maternal protein restriction during gestation modulates the DNA methylation status and significantly upregulates the expression of renal Ptger1 associated with hypertension in offspring." (PMID 37764741, 2023). "This insight underscores the potential relevance of Ptger1’s epigenetic regulation in elucidating the mechanisms underpinning hypertension in this context." (PMID 37764741, 2023).
colon cancer (5 papers, 2008 to 2024). "Intriguingly, deletion of EP1 (Ptger1), EP3 (Ptger3), or some other PG receptor subtypes failed to suppress colon tumor formation but rather exacerbated it, suggesting the presence of PG receptor subtype oppositely functioning to colon tumor formation." (PMID 29259703, 2017).
endometrial cancer (4 papers, 2020 to 2025). Primary or metastatic malignant neoplasm involving the endometrium (mucous membrane that lines the endometrial cavity). "The age-associated increase in PTGER1 expression supports its potential as a diagnostic marker for age-related endometrial cancer." (PMID 41583321, 2025).
nasal polyp (4 papers, 2006 to 2024). "First, we performed reverse transcription-quantitative polymerase chain reaction (RT-qPCR) to examine the mRNA expression levels of mPGES-1 (encoded by PTGES) and PGE2 receptors (EP1–4, encoded by PTGER1–4) in the nasal polyps of ECRS or non-ECRS patients." (PMID 39015572, 2024).
endometriosis (3 papers, 2015 to 2025). The growth of functional endometrial tissue in anatomic sites outside the uterine body. "SSTR5, KCNH2, CASP3, PTGER1, PPARD, and TYMP emerged as the top-ranked targets, indicating their potential significance in the treatment of endometriosis." (PMID 39754173, 2025).
hepatocellular carcinoma (3 papers, 2022 to 2025). A malignant tumor that arises from hepatocytes. "Interestingly, PTGER1 expression was markedly higher in LIHC tissues from both middle-aged (41-60 years) and elderly (61-80 years) patients compared with normal controls, indicating that PTGER1 upregulation may be associated with age-related progression or susceptibility to hepatocellular carcinoma." (PMID 41583321, 2025).
lung carcinoma (3 papers, 2021 to 2025). "Only the expression of GPR54 was associated with CD8+ T cell infiltration in lung cancer, although Grin1 (glutamate receptor), Ptger1 (prostaglandin E receptor 1), Hrh2 (histamine receptor), Ghsr (growth hormone secretagogue receptor), and Tacr1 (substance P receptor) were detected." (PMID 35224894, 2022).
Obesity (3 papers, 2015 to 2025). Accumulation of substantial excess body fat. "Brain transcriptome analyses in obese mice identified several obesity-related pathways (e.g. leptin, somatostatin, and nemo-like kinase signaling), as well as genes involved in feeding and appetite (e.g. Pmch, Neurotensin) and in metabolism (e.g. Bmp4, Bmp7, Ptger1, Cox7a1)." (PMID 25629159, 2015).
adenoma (2 papers, 2006 to 2021). A neoplasm arising from the epithelium. "PTGER1 upregulates the aldosterone‐producing adenoma; its expression remains associated with DNA methylation." (PMID 34535962, 2021).
adrenocortical adenoma (2 papers, 2020 to 2022). "PTGER1 shows a strong association with DNA methylation in non-functioning adrenocortical adenoma." (PMID 31969157, 2020). "PTGER1, one of the prostaglandin receptors, conjugates G-proteins to activate the protein kinase C. DNA methylation is a critical link in tumor transformation, PTGER1 is closely related to DNA methylation in non-functioning adrenocortical adenoma." (PMID 36419120, 2022).
clear cell renal cell carcinoma (2 papers, 2022 to 2025). "In addition, the high-level expression of PTGER1 is correlated with a poor prognosis in clear cell renal cell carcinoma." (PMID 36419120, 2022).
diabetes (2 papers, 2014 to 2016). "Interestingly, diabetes resulted in a significant reduction of Ptger1 and Ptger3 mRNA levels in macrophages; effects that were not mediated by myeloid cell EP4." (PMID 27351842, 2016).
nephrosclerosis (2 papers, 2021 to 2023). Hardening of the kidney due to infiltration by fibrous connective tissue (fibrosis), usually caused by renovascular diseases or chronic hypertension. "We identified 96 tag-SNPs capturing global variability in PTGER1-4 and screened 1209 nephrosclerosis patients and controls." (PMID 34442416, 2021).
urolithiasis (2 papers, 2012 to 2025). Stone(s) within the urinary tract. "Furthermore, elevated PTGER1 levels in obstructed ureters and stable expression across age groups were noted, suggesting a role in maintaining renal homeostasis and potential therapeutic relevance for urolithiasis and other renal pathologies." (PMID 41583321, 2025).
colorectal tumor (1 paper, 2013). "The FCCTX tumors also showed up-regulation of PTGER1, which encodes for the EP1 receptor that may promote proliferation and colorectal tumor development through altered function of prostaglandin E2 (PGE2)." (PMID 23951239, 2013).
endometrial adenocarcinomas (1 paper, 2011). "Here, we undertook a comprehensive analysis of the expression profile of the PGE synthase enzymes (PTGES, -2, -3) and E-series prostanoid receptors (PTGER1–4) in endometrial adenocarcinoma by quantitative RT-PCR analysis." (PMID 21589857, 2011). "Here we investigated (a) the expression profile of the PGE synthase enzymes (PTGES, PTGES-2, PTGES-3) and PGE receptors (PTGER1–4) in endometrial adenocarcinomas compared with normal endometrium and (b) the role of PTGER4 in endometrial tumorigenesis in vivo." (PMID 21589857, 2011). "Here, we show suppression of PTGER1 and PTGER3 and elevated expression of PTGES2 and PTGER4 in endometrial adenocarcinomas compared with normal endometrium." (PMID 21589857, 2011). "We found elevated expression of PTGES2 and PTGER4 and suppression of PTGER1 and PTGER3 in endometrial adenocarcinomas compared with normal endometrium." (PMID 21589857, 2011). "However, more interestingly, within this sample set we found a significant reduction in the expression patterns of PTGER1 and PTGER3 in endometrial adenocarcinomas compared with normal endometrium." (PMID 21589857, 2011).
endometrial tumors (1 paper, 2025). "These cross-platform findings suggest that PTGER1 expression may be cancer type specific, with renal, hepatic, and endometrial tumors showing the most consistent regulatory trends." (PMID 41583321, 2025).
kidney cancer (1 paper, 2025). Primary or metastatic malignant neoplasm involving the kidney. "Consequently, these data imply that immune suppression might not be the primary driver of tumor progression in kidney cancers where PTGER1 is diminished." (PMID 41583321, 2025).
liver cancer (1 paper, 2025). An epithelial or non-epithelial malignant neoplasm that arises from the liver. "This pattern suggests PTGER1 may be transiently upregulated during early and intermediate tumor stages, possibly reflecting a role in tumor initiation or inflammation and its potential use as a diagnostic biomarker for early-stage liver cancer, particularly stage 1 and stage 3." (PMID 41583321, 2025).
lung squamous cell carcinoma (1 paper, 2025). "Subsequently, prognostic analysis indicated that elevated PTGER1 expression was associated with poorer outcomes in KIRC and lung squamous cell carcinoma (LUSC) across three databases and improved prognosis in LIHC." (PMID 41583321, 2025).
osteoporosis (1 paper, 2023). A condition of reduced bone mass, with decreased cortical thickness and a decrease in the number and size of the trabeculae of cancellous bone (but normal chemical composition), resulting in increased fracture incidence. "Then five key genes (CCR5, IAPP, IFNA4, IGHV3-73 and PTGER1) were identified and used as features to construct a predictive prognostic model for osteoporosis using the GSE7158 dataset." (PMID 37361541, 2023).
renal carcinoma (1 paper, 2025). A carcinoma arising from the epithelium of the renal parenchyma or the renal pelvis. "PTGER1 emerges as a promising candidate diagnostic biomarker for renal cancers, due to its consistent and significant downregulation across three independent datasets: TIMER, GEPIA, and UALCAN." (PMID 41583321, 2025). "Overall, PTGER1 expression profiling across TIMER, GEPIA, and UALCAN consistently revealed significant downregulation in renal cancers, particularly KICH and KIRC, highlighting a reproducible suppression pattern across platforms." (PMID 41583321, 2025).
Ureteral obstruction (1 paper, 2012). Obstruction of the flow of urine through the ureter. "Prostaglandins play an important role in ureteral obstruction, but the detailed expression profiles of the prostaglandin receptors (PTGER1, PTGER2, PTGER3, PTGER4, PTGFR) remain unknown in the different parts of the human ureter." (PMID 23227994, 2012).
tumor (47 papers, 2006 to 2026). "PTGER1, a G protein-coupled receptor, mediates the effects of prostaglandin E2, a molecule that has been implicated in various malignancies by promoting tumor growth and metastasis through inflammatory pathways." (PMID 41583321, 2025). "Our findings aim to enhance the understanding of PTGER1’s contribution to tumor pathogenesis, improve diagnostic and prognostic precision, guide the development of more effective and broadly applicable therapeutic strategies, and bridge the gap between basic research and clinical oncology." (PMID 41583321, 2025). "In BLCA, normal tissues exhibited hypermethylation while tumor tissues displayed hypomethylation, coinciding with PTGER1 upregulation in malignant cells." (PMID 41583321, 2025). "In contrast, an insignificant downregulation of PTGER1 in tumor samples was observed in LUAD, BLCA, and GBM, and an insignificant upregulation in LIHC and UCEC." (PMID 41583321, 2025). "Comprehensive evaluation of PTGER1 expression across nine TIMER revealed distinct tumor-specific alterations." (PMID 41583321, 2025). "Initial analysis using the TIMER database allowed a broad comparative assessment of PTGER1 expression across multiple human cancer types, providing foundational insights into its tumor-specific regulation." (PMID 41583321, 2025). "In KICH, PTGER1 expression was significantly (P<0.0001) upregulated in normal tissue compared to Caucasian tumor samples and showed an insignificant upregulation in normal samples when compared with African American patients and Asian patients." (PMID 41583321, 2025). "PTGER1 expression was systematically profiled in tumor versus normal tissues using three publicly accessible platforms: TIMER, GEPIA, and UALCAN." (PMID 41583321, 2025). "In terms of tumor staging, PTGER1 expression showed a significant difference between normal and tumor tissues in both KICH and KIRC (P<0.0001), with elevated expression levels in normal tissues and dramatic downregulation in tumor samples." (PMID 41583321, 2025). "This suppression pattern suggests a potential role for PTGER1 in kidney-specific tumorigenesis or tumor suppression." (PMID 41583321, 2025). "PTGER1 expression in UCEC increases consecutively across tumor stages, suggesting a potential role in late-stage tumor diagnosis, though this pattern warrants further validation." (PMID 41583321, 2025). "TCGA analysis via publicly available databases, GEPIA, UALCAN, and TIMER, demonstrated that PTGER1 was consistently downregulated in tumor samples when compared with normal samples in KICH and KIRC across the three databases." (PMID 41583321, 2025). "This approach provides a comprehensive view of PTGER1's potential role in modulating the tumor immune microenvironment." (PMID 41583321, 2025). "This is concordant with PGE2 being the major prostanoid in tumor microenvironments and fits previous observations in ApcMin transgenic mice, where deletion of PTGER1, PTGER2, and PTGER4 inhibits the development of CRC." (PMID 26207152, 2015). "In BLCA, PTGER1 was hypermethylated in normal tissues, while tumor tissues were hypomethylated, correlating with its upregulation in tumors, suggesting that loss of methylation may drive increased expression." (PMID 41583321, 2025). "In contrast, in HNSC, PTGER1 shows both hypermethylation and upregulation in tumor tissues." (PMID 41583321, 2025). "Lastly, a statistically significant (P<0.0001) hypermethylation of PTGER1 occurred in UCEC tumor tissue samples, while higher expression in normal tissues aligns with hypomethylation-driven regulation, supporting methylation as a suppressive mechanism in this case." (PMID 41583321, 2025). "Laboratory-based studies, including gene manipulation and functional assays in cell or animal models, are needed to verify whether PTGER1 directly influences tumor behaviour or immune regulation." (PMID 41583321, 2025).
tumor (continued). "Despite downregulation of PTGER1 expression, a weak immunological response may still drive tumor pathology." (PMID 41583321, 2025). "Additionally, PTGER1 is associated with altered immune cell infiltration patterns, suggesting that PTGER1 may play a role in modulating the tumor immune microenvironment and can serve as a target for immune therapeutic interventions." (PMID 41583321, 2025). "Recent studies have highlighted the role of various prostanoid receptors in modulating inflammatory pathways, suggesting that dysregulation of PTGER1 could contribute to the tumor microenvironment's inflammatory state, potentially exacerbating cancer progression." (PMID 41583321, 2025). "PTGER1 is strongly expressed in normal kidney and consistently downregulated across all tumour stages in KICH and KIRC, supporting a tumor suppressive role." (PMID 41583321, 2025). "PTGER1 expression in UCEC showed a statistically significant difference across racial groups; normal tissue samples had higher expression compared to Caucasian tumor samples." (PMID 41583321, 2025). "The observed age-dependent increase in PTGER1 expression suggests that its regulation is influenced not only by tumor stage but also by aging, as its expression is not static across the lifespan." (PMID 41583321, 2025). "In KIRC, statistically significant (P<0.0001) differences were identified between normal tissue and tumor samples in patients aged 21-40 years, 41-60 years, 61-80 years, and 81-100 years, demonstrating a consistent downregulation of PTGER1 irrespective of age." (PMID 41583321, 2025). "Similarly, PTGER1 expression in KIRC and KICH was higher in normal tissues than in tumor samples when grouped by patient age." (PMID 41583321, 2025). "This raises the question whether reduced PTGER1 expression in KIRC and KICH could indicate a context-dependent role of EP1, potentially reflecting a shift away from immune modulation toward alternative tumor-promoting pathways." (PMID 41583321, 2025).